INS (insulin)
Diseases named in the same sentence as INS in open-access papers (continued):
Sharing a sentence is not in itself a finding about the gene and the disease.
Hypoglycemia (continued). "Hyperinsulinaemic hypoglycaemia (HH) is the inappropriate secretion of insulin in the presence of low plasma glucose levels and leads to severe and persistent hypoglycaemia in neonates and children." (PMID 29280746, 2017). "Treatment of cultured pancreatic beta cells with plasma from patients with malaria-induced hypoglycemia resulted in a significant increase in insulin secretion." (PMID 29216326, 2017). "The patients that subsequently had hypoglycaemia did have a significantly higher insulin peak suggesting an increased insulin response to glucose concentrations, i.e. an increased insulinogenic index." (PMID 28855269, 2017). "Compared against other specific active treatments, a combination of insulin glargine plus glimepiride and metformin demonstrated significantly fewer hypoglycaemic events (both confirmed and unconfirmed hypoglycaemia) compared to premixed insulin." (PMID 29047344, 2017). "Individuals with altered HPAA and insulin-induced hypoglycemia are affected by an increased stress response." (PMID 29077038, 2017). "Results from this study indicated that, compared to participants with NGT, participants with biochemical hypoglycemia had higher levels of insulin sensitivity, as well as higher levels of β-cell function, both in the early and late stages." (PMID 28913363, 2017). "The data presented show that while ICT can achieve insulin independence for a proportion of recipients, it is most effective at resolving problematic hypoglycemia." (PMID 28293906, 2017). "In summary, the use of glyburide in pregnancy for women with GDM appears to be as effective as the use of insulin, but neonatal hypoglycemia should be monitored." (PMID 28771572, 2017). "Hypoglycemia occurred in eleven patients (68.7%) who had received insulin degludec once in the evening or at bedtime and in five patients (31.3%) who had received insulin degludec once in the morning." (PMID 28683068, 2017). "The addition of glucagon in the dual-hormone (insulin and glucagon) system can further reduce hypoglycaemia but limited data exist so far to quantify the improved safety compared with the single-hormone system with announced physical activity." (PMID 28840263, 2017). "Blood samples obtained during hypoglycemia showed insulin: 8.0 μIU/mL, adrenocorticotropic hormone (ACTH) > 1250 pg/mL, cortisol: 57.3 μg/dL." (PMID 28420223, 2017). "Compensatory measures in the brain during chronic insulin-induced hypoglycaemia are less well understood." (PMID 28421113, 2017). "Although severity of hypoglycaemia was significantly greater with insulin therapy, the number of episodes of hypoglycaemia experienced was similar." (PMID 27896444, 2017). "Here we have retrospectively analyzed a large group of patients with acute or chronic kidney disease to assess the development of hypoglycemia following an intravenous infusion of insulin plus glucose to treat an episode of hyperkalemia." (PMID 28245289, 2017). "Treatment strategies for lean participants with T2DM should therefore be multimodal with lifestyle modification, antihypertensive therapy, lipid lowering therapy and antihyperglycemic therapy avoiding hypoglycemia and insulin therapy, where possible." (PMID 28827839, 2017). "After hypoglycemia was corrected, the level of insulin was 22.9 μIU/mL, ACTH was 18.86 pg/mL, and cortisol was 17.76 μg/dL." (PMID 28420223, 2017). "The results indicated that insulin induced hypoglycemia in a dose-dependent manner resulting in a significant reduction in %GR of liquid only at the highest dose tested (1 U/kg)." (PMID 28876363, 2017). "Brain tissue levels of the astrocytic glucose transporter GLUT1 were unchanged by insulin-induced hypoglycaemia, in line with other studies with hypoglycaemia of shorter duration (8–12 days)." (PMID 28421113, 2017). "We recommend surgery for all cases of localised insulinoma, with transoperative control of hypoglycemia (US with dosages of insulin and glucose)." (PMID 28194228, 2017).
Hypoglycemia (continued). "In terms of insulin secretion, participants with biochemical hypoglycemia showed higher secretion levels of Ins30 but lower secretion levels of Ins120." (PMID 28913363, 2017). "Hypoglycemia, on the other hand, is an important side effect of pharmaceutical blood glucose control, especially those who are treated with insulin." (PMID 29188156, 2017). "The reduction in insulin doses alongside an appropriate dietary plan permitted the significant reduction in the frequency of hypoglycemia, which went down from 1.3 episodes per camper per day at the beginning to 0.5 at the end of the camp." (PMID 26791079, 2016). "Hypoglycaemia suppresses insulin secretion from β-cells and stimulates glucagon secretion from islet α-cells, normalizing blood glucose levels." (PMID 27044683, 2016). "Nocturnal HBGI and CONGA2, along with HbA1c and daily insulin dose, were independent predictors for sympathetic activity at subsequent hypoglycemia." (PMID 27066358, 2016). "The patient was not qualified for a surgery due to confusing results of the laboratory findings (mainly postprandial hypoglycemia with normal serum insulin and C-peptide concentrations were observed)." (PMID 27526057, 2016). "We previously showed that insulin-induced hypoglycemia led to retinal cell death, possibly through a modification of glutathione (GSH) metabolism that alters GSH level of the cell." (PMID 26918849, 2016). "Factors that are associated with an increased risk of hypoglycemia in CKD patients include decreased renal gluconeogenesis, deranged metabolic pathways (including altered metabolism of medications) and decreased insulin clearance." (PMID 27471550, 2016). "We observed one metabolic complication, an insulin-requiring diabetic who developed hypoglycemia both while taking the bowel preparation and again 2 days after colonoscopy." (PMID 27446832, 2016). "The present study shows that GCLM-KO mice present with lower plasma glucose and insulin levels, and a reduced ability to increase plasma glucose in response to insulin-induced hypoglycemia or to acute stress." (PMID 27148080, 2016). "More importantly, our findings fully reveal that the gain of miR-155 function leads to hypoglycemia and improved glucose tolerance through induction of insulin insensitivity in peripheral tissues, thereby improving whole-body glucose metabolism." (PMID 27711113, 2016). "Rates of severe hypoglycemia are approximately of 1.15 events/patient-year, and can reach 3.2 events/patient-year in type 1 DM patients; in insulin-treated type 2 DM patients, rates are 0.7 events/patient-year." (PMID 26740822, 2016). "Our data, and that of others, in both rodents and humans suggest that early in pregnancy relative hypoglycemia is evident even as insulin secreting capacity and β-cell proliferation are manifest." (PMID 27559358, 2016). "In the present study, the insulin glargine group had a numerically lower rate of any hypoglycaemia per patient year than the NPH insulin group (68.6 ± 69.4 versus 84.6 ± 79.3)." (PMID 27887605, 2016). "Growth retardation, hypoinslulinemia, hypoglycemia and increased insulin sensitivity have been reported in mice with defective growth hormone receptors (GHRs)." (PMID 27293546, 2016). "The group that had experienced moderate hypoglycemia symptoms used significantly higher doses of insulin and snacked more often than other groups." (PMID 27994961, 2016). "Compared with insulin glargine and detemir, degludec promotes flatter PK/PD profiles, decreasing the number of confirmed hypoglycemia episodes." (PMID 26740822, 2016). "The occurrence of unfavorable outcomes either in pregnancy or in neonate were not raised in those who were managed with metformin compared with those who were managed with insulin except the fact that the neonatal hypoglycemia happened more in insulin group." (PMID 27597988, 2016).
Hypoglycemia (continued). "Overall development of insulin aims to decrease patients’ hypoglycemia episodes and improve pharmacokinetics (PK)/pharmacodynamics (PD) profile, by mimicking as close as possible the normal insulin release." (PMID 26740822, 2016). "The nocturnal HBGI and CONGA2, along with HbA1c and daily insulin dose, were predictors of LF during daytime hypoglycemia in multiple regression analysis (b = −1.4, b = −0.61, b = −1.24 and b = −0.73, respectively, R2 = 0.51, p = 0.008)." (PMID 27066358, 2016). "Another issue is that slight hypoglycemia often develops 30–45 min after a glucose infusion given to a subject with high insulin sensitivity." (PMID 26759716, 2016). "Biochemically, insulin, proinsulin, C-peptide, growth hormone and β-hydroxybutyrate levels are low at the time of hypoglycemia, as was observed in this patient." (PMID 27905899, 2016). "Serum levels were: insulin 42.5 μU/mL, cortisol 10.9 mg/dL, growth hormone 32.1 ng/mL, and C-peptide 2.7 ng/mL at the time of hypoglycemia (blood glucose level 32 mg/dL)." (PMID 27181099, 2016). "Her hypoglycemia workup revealed an insulin level of 6 μU/mL (relatively elevated for a blood glucose of 44 mg/dL), negative urine ketones, low beta-hydroxybutyrate, and hyperammonemia (150 to 200 μmol/L)." (PMID 26839063, 2016). "Results of t-test between severity of hypoglycemia and A1c, dose of insulin and number of snacks (n = 187)." (PMID 27994961, 2016). "The inappropriate release of insulin leads to persistent severe hypoketotic hypofattyacidemic hypoglycemia and most of the cases present in the neonatal period." (PMID 27181099, 2016). "A significant relationship was found among the dose of insulin, the number of daily snacks, and the severity of hypoglycemia." (PMID 27994961, 2016). "These impairments first include the inability to decrease insulin and to increase glucagon in response to hypoglycemia." (PMID 26521082, 2016). "In recent years, it has gradually been recognized that lactate plays an important role in the energy metabolism in the brain, particularly during hypoglycemia since both hypoglycemia and insulin increase plasma levels of lactate, at least in healthy subjects." (PMID 26521082, 2016). "Twenty-one patients presented with hypoglycaemia at a median age (range) 1 day(1 day, 8 months) with glucose 1.7(0.1, 2.6) mmol/L, insulin 97.2(16.8, 234.0) pmol/L and glucose infusion rate 14.9(10.0, 20.0) mg/kg/min." (PMID 27908292, 2016). "The PB insertion effectively blocks Otg1 expression, which results in postnatal lethality, growth retardation, hypoglycemia and improved insulin sensitivity in mice." (PMID 27293546, 2016). "The increase in the frequency of hypoglycemia recorded at the beginning of the camp should lead to the systematic reduction of insulin doses on arrival at camp, especially in well-controlled campers." (PMID 26791079, 2016). "Incidence rates of drug-induced hypoglycemia were the highest for basal insulin and sulfonylureas: 8.64 and 4.32 events per person-year in 65–79 year olds, and 12.06 and 6.03 events per person-year for 80 years and older." (PMID 27648831, 2016). "Patients with HI/HA exhibit increased sensitivity to protein (leucine) stimulation of insulin release, leading to protein-induced hypoglycemia." (PMID 26962538, 2016). "The pathogenesis of hypoglycemia in these patients is related to changes in glucose metabolism, decreased insulin degradation, and changes in the metabolism of hypoglycemic agents." (PMID 27471550, 2016). "In order to minimize hypoglycemia or hyperglycemia episodes, insulin analogues with different PK/PD profiles were developed, including basal and ultra-long basal insulins." (PMID 26740822, 2016). "When glucose levels in the low-physiological range (e.g. late post-absorptive or fasting state) tend to fall, insulin secretion is suppressed to such an extent that true hypoglycemia can almost always be prevented." (PMID 26521082, 2016).
Hypoglycemia (continued). "Patients treated with insulin usually face the same problems as those with type 1 diabetes, except for the fact that the incidence of hypoglycemia is lower." (PMID 27148163, 2016). "The laboratory examination reported hypercalcemia with inhibited PTH and hypoglycemia with inhibited insulin secretion, arriving to the conclusion of tumoral peptide production." (PMID 27737327, 2016). "The aim of the present study, the HAT study, was to examine the impact of hypoglycaemia in an insulin‐using global patient population in an epidemiological observational study covering a 6‐month retrospective and a 4‐week prospective time period." (PMID 27161418, 2016). "In our laboratory, we have adopted the i.p method of insulin administration to induce single or recurrent hypoglycaemia and observed that this route successfully reduced the blood glucose levels consistently throughout our experiments." (PMID 27843452, 2016). "Compared with insulin, all GLP-1 RAs except for dulaglutide reduced the risk of hypoglycemia with range from 0.38 (95%CrI: 0.18, 0.78) to 0.63 (95%CrI: 0.43, 0.93)." (PMID 27158818, 2016). "For example, a hyperactive mutation of AKT2, the gene required for insulin-induced translocation of GLUT4 to the plasma membrane, caused hypoinsunlinemic hypoglycemia in four patients." (PMID 27293546, 2016). "Global transgenic overexpression of miR-155 in mice leads to hypoglycaemia, improved glucose tolerance and insulin sensitivity." (PMID 27711113, 2016). "The DSMP, which includes domains regarding diet, exercises, insulin, blood glucose monitoring frequency, and hypoglycemia, showed to have the most powerful questions to predict glycemic control when compared to self-evaluations." (PMID 27478510, 2016). "The group that had experienced severe hypoglycemia symptoms used significantly higher doses of insulin than other groups." (PMID 27994961, 2016). "History of past hypoglycemia and insulin treatment are known and important predictors of a future hypoglycemic event, and, as stated in different recommendations, are important aspects to consider when assigning a patient to a certain HbA1c target." (PMID 26887662, 2016). "The study design and the pharmacodynamic profile of IDegAsp probably had a strong impact on the results; specifically on the rate of overall confirmed hypoglycemia, insulin dose, FPG and prandial glucose control as well as on body weight in the IDegAsp group." (PMID 27760129, 2016). "Observational studies report that hypoglycemia occurs in up to 42.89 events/patient-year, in type 1 DM patients, and in up to 16.36 events/patient-year in insulin-treated type 2 DM patients." (PMID 26740822, 2016). "Hypoglycemia developed in 7 babies of metformin group and 15 cases in insulin group with P value 0.01 which is statistically significant." (PMID 27597988, 2016). "Compared with conventional insulin pump therapy, mean sensor glucose on days 2–5 were reduced by 1.7 mmol/l (p = 0.0037) and the time spent with hypoglycaemia was also reduced (p < 0.0001)." (PMID 27364997, 2016). "Thirdly, it reminds practitioners that hypoglycaemia can occur in PWD on insulin and those on oral medication." (PMID 27380790, 2016). "In studies where 10 units of insulin were infused, the fewest cases of hypoglycemia were seen in patients given 50 grams of glucose." (PMID 27148740, 2016). "CHI was defined as an inappropriately elevated insulin level (100 pmol/L) during hypoglycaemia (2 mmol/L) with suppressed fatty acids (<100 μmol/L) and 3-hydroxy butyrate (<100 μmol/L)." (PMID 27087264, 2016). "Compared with the control therapy, the number of episodes of hypoglycaemia with sensor glucose values below 3.5 mmol/l was significantly reduced (p = 0.003) with overnight closed-loop insulin therapy, with comparable median glucose levels." (PMID 27364997, 2016). "A number of studies have performed i.p administration of insulin to induce antecedent hypoglycaemia." (PMID 27843452, 2016).
Hypoglycemia (continued). "Annual costs of hypoglycemia for older adults attaining very tight glycemic control with the use of insulin or sulfonylureas were estimated at U.S.$509,214,473 in the U.S. and CAN$65,497,849 in Canada." (PMID 27648831, 2016). "The brain, in particular the hypothalamus, is involved in the control of peripheral glucose homeostasis through regulating hepatic glucose output, pancreatic insulin secretion, and counterregulatory responses to hypoglycemia." (PMID 27740870, 2016). "In conclusion, IDegAsp OD provides predictable, efficacious fasting and prandial glycemic control in insulin-naïve patients with T2DM in a single injection, while significantly reducing the risk of nocturnal-confirmed hypoglycemia compared with IGlar." (PMID 27760129, 2016). "Hypoglycemia is the most serious and fatal complication for fasting and for many treatment options for diabetes, such as insulin and some of the oral glucose-lowering therapies, including sulfonylurea (SU) and meglitinides." (PMID 27642611, 2016). "Hypoglycemic medications including insulin were completely withdrawn over 3–6 months due to either recurrent hypoglycemia in six patients or tight glycemic control (HbA1c ≤6%) in the other two patients." (PMID 28031949, 2016). "Logistic regression analysis adjusted for age, gender, duration of disease and total basal insulin confirmed significant positive correlations of VI with severe hypoglycemia (β = 0.013; p<0.001) and diabetic ketoacidosis (β = 0.012; p = 0.017)." (PMID 26938444, 2016). "Two more sets of animals received saline once or twice on the first two days and insulin once on the third day to represent the single hypoglycaemia groups (Sal Sal Ins; Sal2 Sal2 Ins)." (PMID 27843452, 2016). "Here, we report our experience with intraoperative portal vein insulin assay combined with occlusion of the pancreas in the management of pancreatogenous hypoglycemia." (PMID 27367988, 2016). "At the time of hypoglycemia, these patients have inappropriately elevated serum insulin levels, low fatty acid and low ketone body levels." (PMID 26839063, 2016). "The incidence of hypoglycemia in patients receiving an insulin dose of <29.7 units or ≥29.7 units was 27.5 % (n = 11) or 32.3 % (n = 10), respectively, in the placebo group and 39.5 % (n = 15) or 40.5 % (n = 15), respectively, in the canagliflozin group." (PMID 27316668, 2016). "The immunohistological and RT-PCR results suggest that insulin-induced hypoglycemia results in an increased expression of the stress-sensitive and pain-related factor c-Fos in nerve tissues." (PMID 26824041, 2016). "When the patient developed hypoglycemia, his serum insulin concentration was 1.7 μIU/mL, C-peptide was 0.04 ng/mL, and blood glucose was 40 mg/dL." (PMID 27957352, 2016). "It is recognized that insulin can be an appetite stimulant in normal individuals, mediated by hypoglycemia." (PMID 26903946, 2016). "It was shown that insulin treatment or endogenous insulin increase normalized the response of the HPA axis to hypoglycemia." (PMID 27563309, 2016). "After a few hours, the blood glucose levels decrease with corresponding insulin concentrations, and the bound insulin is released from the antibodies, resulting in the hypoglycemia." (PMID 27065949, 2016). "Logistic regression analysis adjusted for age, gender, duration of disease and total basal insulin confirmed significant correlations of the variability index with severe hypoglycemia (β = 0.013; p<0.001) and diabetic ketoacidosis (β = 0.012; p = 0.017)." (PMID 26938444, 2016). "A possible reason for this is the overly cautious approach to insulin initiation and titration, which, in turn, is thought to be a result of physician anxiety about invoking events of hypoglycemia in patients." (PMID 27669747, 2016). "Non-islet hypoglycemic cell tumor consists of a rare syndrome characterized by the presence of a solid tumor and severe fasting hypoglycemia determined by an insulin-independent pathway." (PMID 27737327, 2016).